KIT (KIT proto-oncogene, receptor tyrosine kinase)
Diseases named in the same sentence as KIT in open-access papers (continued):
Sharing a sentence is not in itself a finding about the gene and the disease.
cancer (continued). "In all, 12 carcinomas presented with distinct KIT overexpression and amplification of KIT gene was considered as a possible mechanism for overexpression." (PMID 15583695, 2004). "KIT expression was detected in 12% of carcinomas: low expression in 10% and high expression in 2% of cases." (PMID 15583695, 2004). "Finally, somatic mutations in KIT itself are the main cause of cancer, but this finding suggests that the function of KIT in different types of cancer is partly regulated by miR-221/222-3p." (PMID 41602427, 2026). "In addition, treatment with clinical antgonists of kinases involved in cancer such as BRAF or c-KIT induces OXPHOS-addiction that limits drug efficacy and simultaneously induces sensitivity to OXPHOS inhibition as combination therapy." (PMID 40597978, 2025). "Thus, we should highlight the combination therapies in future cancer treatments, including radical surgery and targeted therapy like c-KIT inhibitor." (PMID 39744440, 2025). "CD117 (KIT) is a tyrosine kinase receptor involved in cell growth and cancer development." (PMID 40271490, 2025). "Taken together, these results indicated that KIT-d could specifically target the KIT protein on cancer cells." (PMID 40963922, 2025). "Because AKT activation is essential for anti-apoptosis signaling in mutant KIT-addicted cancer cells, the cleavage of AKT may serve as a positive feedback mechanism for M-COPA-induced apoptosis." (PMID 38679330, 2024). "Activation of VEGF/VEGFR signaling in IM-resistant GIST cells might be a result of FGF2 production by KIT-inhibited cancer cells, which in turn leads to the production and secretion of VEGF-A, and thereby activates VEGFR-mediated cascade." (PMID 39272961, 2024). "According to the anti-cancer drug target information of GDSC, there are only one druggable gene (KIT) in the BrC24 and the connectivity loss scores of KIT was significantly larger in the individualized gene networks of the samples belonged to the second cluster (P-value = 1.24E-45)." (PMID 38622359, 2024). "Concomitant amplification of KIT and MDM2/4 may be associated with resistance to anti-cancer immune therapy; thus, the importance of adequately providing the MDM2 assays." (PMID 38732333, 2024). "Additionally, genes such as VEGFA on chromosome 12, and KDR and KIT on chromosome 13, are frequently amplified in these cancers." (PMID 39872607, 2024). "In addition, 6e showed a strong inhibition in the growth of KIT-dependent GIST cancer cells, such as GIST-T1 (GI50 = 0.021 μM) and GIST-882 (GI50 = 0.043 μM)." (PMID 37298401, 2023). "The protein encoded by the KIT gene, c-KIT, is a stem cell growth factor receptor, one of the type III receptor tyrosine kinases known to play a critical role in the onset and proliferation of cancer." (PMID 37427115, 2023). "Accordingly, we investigated expression profiles of cells within clusters 1 and 2 and found that 275 genes were expressed significantly in these cells compared with cells in other clusters, including SOX9, KRT5, a basal marker, and KIT, which is often overexpressed in tuft cell-like cancers." (PMID 37179317, 2023). "However, SCF is still able to bind to mutant KIT and induce its internalization, which makes it a potential vector to deliver drugs into cancer cells." (PMID 38313431, 2023). "For example, the associations between polyploidy and the activation of pathways of meiosis, female gametogenesis, programs of unicellularity, and signaling of multipotency (TGFbeta, JAK-STAT, c-KIT) were well documented in heart diseases, cancer, and normal tissues." (PMID 37108224, 2023). "ADC NN2101-DM1 is effective to KIT-expressing cancer in xenograft mouse model." (PMID 35999600, 2022). "In relapsed patients, stem-like cancer cells showed increased expression of KIT." (PMID 35887076, 2022).
cancer (continued). "This suggests that the use of combination therapies involving novel anti-KIT ADCs in conjunction with standard chemotherapeutic agents, TK inhibitors, or other targeted agents, should be considered a strategy to enhance the efficacy of anti-KIT ADCs used as a monotherapy for different cancer types." (PMID 35490363, 2022). "Both the downregulation and upregulation of KIT signaling have been reported in human cancers." (PMID 35563085, 2022). "This suggested that Wee1 plays a potential role in the regulation of KIT in GIST which may contribute to an anti-proliferative effect of Wee1 inhibition in this cancer." (PMID 35965531, 2022). "Although a majority of triple-negative mammary carcinomas shows strong expression of KIT, activating mutations of KIT in this type of cancers seem to be rare in humans." (PMID 36396684, 2022). "Not only the c-KIT protein but also another tyrosine kinase family receptor, i.e., vascular endothelial growth factor receptor (VEGFR), has also involved in progression of cancer development, mainly due to mutation or upregulation/overexpression of VEGFR." (PMID 36354673, 2022). "Squamous cell and undifferentiated—non-neuroendocrine—carcinomas were the most frequent subtypes in our cohort, and featured KIT mutations in 9%-10% of cases." (PMID 35749302, 2022). "In this context, IHC assessment of c-KIT is a valuable diagnostic tool since its expression is found in more than 90% of mammary ACC but not in other carcinomas with overlapping histologic features." (PMID 35490363, 2022). "The authors of this study identified several receptor tyrosine-protein kinases (RTK) in the drug resistance of NSCLC cells, including ERRB4, KIT, and Tie1, and suggested that the inhibition of RTKs may sensitize cancer cells to paclitaxel." (PMID 33461544, 2021). "As such, the use of drugs targeting c-KIT has provided a novel approach for cancer treatment." (PMID 33918490, 2021). "Imatinib, as a potent PDGFR, tyrosine kinase and KIT inhibitor has been successfully used in treating cancer, and thus could provide an alternative treatment strategy in neurovascular diseases." (PMID 32260484, 2020). "KIT is the genetic driver of several malignant tumors: the majority of GIST and mastocytoses harbor this gene mutation and during the progression of AML, KIT mutation may also be acquired." (PMID 31848942, 2020). "Thus, we will examine the relationship between KIT localization and oncogenic signaling in these cancers in the near future." (PMID 31484543, 2019). "Ponatinib has been shown to bind KIT, but is not approved for KIT-associated cancer types and clinical data are therefore lacking." (PMID 30146241, 2018). "As just one example, this approach could be adopted for cancers that are also driven by transcription factors, such as c‐Myc, KIT, and ER." (PMID 30108134, 2018). "For these reasons, a more selective inhibitor of mutant-KIT isoforms may be desirable to more specifically target KIT D816-mutant cancers such as SM and CBF AML." (PMID 29137311, 2017). "This may suggest the critical function of KIT in vivo except for its contribution for the cancer progression." (PMID 29050270, 2017). "The reduction in cell viability induced by MIR494 has been observed in other cancer types; indeed, several MIR494 targets have been thus far identified which are associated with reduced cellular survival including IGF2, c-KIT, HOXA10, CLPTM1L, SCGN, CXCR4, and c-myc." (PMID 26794413, 2016).
cancer (continued). "Finally, their effects on c-KIT mRNA and protein expression were evaluated in a panel of human cancer cell lines, including also some well-known in vitro models of c-KIT-dependent tumors." (PMID 26942875, 2016). "Those pathways specifically altered in primary tumors were associated with an abnormally increased expression of genes that are involved in focal adhesion (e.g., PRKCA, CRK, and BCL2), PI3K-Akt signaling (e.g., PHLPP2, PRKCA, PPP2R3A and KIT) and cancer pathways (e.g., COL4A5, LAMC1 and BCL2L1)." (PMID 27662660, 2016). "Previously, we found that p55PIK activated the NF-κB pathway in several cancer lines, so we examined whether p55PIK regulated KIT expression in GIST via the NF-κB signaling pathway." (PMID 26587973, 2016). "Therefore, it is most likely that oncogenic potential of different KIT mutants profoundly dependent on host cell type or cancer type." (PMID 27777718, 2016). "We sequenced 297 loci from 3 cancer-related genes (KIT, PDGFR and BRAF only in wild type GIST)." (PMID 25885906, 2015). "Sequence variations (SNP) of KIT have been described to play an important role in cancer." (PMID 26498480, 2015). "The analysis of results from MethHC, a database of DNA methylation and mRNA expression profiles in human cancer showed that hyper-methylation in the promoter region of c-KIT proto-oncogene induced the down-regulation of gene expression in most cancer tissues such as colon adenocarcinoma." (PMID 26607501, 2015). "Similarly, in another cancer registry-based study of 46 c-KIT confirmed cases diagnosed in 1994–2001, women had a better 5-year survival than men (75% vs. 52%)." (PMID 24548660, 2014). "Notably, the co-gained regions included a small array of genes (human chromosome 4, zebrafish chromosome 20) that contains KDR, PDGFR and KIT; three genes identified as cancer drivers and potential drug targets in human MPNSTs." (PMID 24009526, 2013). "KIT has also been reported to play an equally important role in various human cancers." (PMID 24073198, 2013). "There are two mechanisms of activation of KIT in malignant tumors." (PMID 23420128, 2013). "KIT amplification, auto-phosphorylation of EGFR, and aberrant expression of other receptor tyrosine kinases have also been postulated by in vitro experiments to cause resistance to crizotinib in ALK-rearranged cancer cells." (PMID 24279718, 2013). "The ligands were able to markedly inhibit KIT expression suggesting that this class of compounds could be promising G4 ligands to target KIT-expressing cancer cells." (PMID 24108400, 2013). "For example, on the 3′ UTR of cancer gene KIT, there is an atypical binding domain for miRNA-221." (PMID 22348086, 2012). "Our results indicate that mutations in c-KIT may be of prognostic significance and that targeting KIT may be a rational approach to treatment of these malignant tumors." (PMID 20950418, 2010). "There are examples of cancer mutations displaying a subgroup level of conservation, including EGFR-L858 position, which bears a conserved leucine in EGFR and ABL kinases, or a conserved aspartate shared in FLT3, KIT, MET, PDGFRα." (PMID 19834613, 2009). "The crystal structures of FLT3, KIT and MET kinases have suggested that cancer mutations may destabilize the autoinhibited wild-type (WT) form." (PMID 19834613, 2009). "Moreover, even in cancer like GISTs driven by other kinases, activation of KIT or PDGFR-α lead to phosphorylation of ERK 1/2 and these kinases mediate the proliferative advantage of the neoplastic cells." (PMID 20003259, 2009). "SCF and its receptor KIT which is known to be an oncoprotein are involved in several cancer types." (PMID 19267929, 2009). "Moreover, it reinforces the role of Kit during development of the liver and underscores the caution that should be exerted in using KIT inhibitors during anti-cancer treatment." (PMID 17612398, 2007).
cancer (continued). "Similarly, other benign variants such as ERBB2 p.Ile655Val, and KIT p.Met541Leu were identified in the present study, suggesting no pathogenic effect despite being located in cancer-related genes." (PMID 40725233, 2025). "While G4s have been predominantly associated with the promoters of oncogenes such as MYC, KIT or KRAS, where their stabilization is associated with suppressed oncogene expression, we explored their potential role in exonic regions and the associated impact on genomic instability in cancer patients." (PMID 38407356, 2024). "Similarly, genes coding for multiple cytokines and surface protein markers that are known to be associated with the basal phenotype, pluripotency, and cancer aggression, such as CD44, KIT, EGFR, and PROM1, were also significantly upregulated in the BORGHigh tumors." (PMID 39335212, 2024). "The presence of mutations in KIT is not used as a diagnostic biomarker for any feline cancer." (PMID 38787171, 2024). "Interestingly, SNAI1-KO cells presented higher stem cell frequency and underwent a switch in the expression of cancer stemness signaling genes, with significant upregulation of epithelial KIT, ALDH1A1 and SOX2, and analogous downregulation of mesenchymal CD44 and SOX9." (PMID 36171192, 2022). "Moreover, activation of KIT is able to promote EMT phenomenon in cancers." (PMID 35768408, 2022). "Furthermore, G4-stabilizing ligands reduce KIT expression in carcinoma cell lines." (PMID 36555662, 2022). "In the era of precision medicine, cancer genome profiling by targeted gene panel analysis may enable potential targeted therapy even for GISTs without KIT or PDGFRA mutations." (PMID 34202544, 2021). "Inhibiting the expression of KIT could improve the prognosis of patients with cancer." (PMID 34582363, 2021). "Besides its potent activity against most major clinically relevant KIT mutations, several studies highlight ponatinib as a multi-targeted inhibitor, which acts as a pan-FGFR inhibitor in different FGFR-amplified or FGFR-mutated cancer cell lines." (PMID 32392832, 2020). "However, the Chi-squared test χ2 revealed, after exclusion of gender-specific cancer diseases, five different genetic mutations that are significantly more common in men than in women: CDKN2A (p = 0.04), CTNNB1 (p = 0.002), KIT (p = 0.0005), SLX4 (p = 0.034), and VHL (p = 0.046)." (PMID 33114048, 2020). "Therefore, in the present study, we investigated - using RNA-Seq- the AQ1-induced effects on the global gene expression in two species-specific KIT-dependent cancer cell lines, in order to identify which cellular pathways are likely to be affected by treatment." (PMID 30459395, 2018). "It suggested that KIT might be used as biomarker or as target of cancer therapies." (PMID 29050270, 2017). "Once the importance of emerging genetic alternations is established in these cancers, such asMET amplifications,ROS1 andRET rearrangements, andHER2 mutations, the OncoFOCUSTM+KIT screening panel could be expanded to facilitate more complete molecular diagnosis." (PMID 28163892, 2016). "These variants were found in over 45% of the cohort and occurred in genes with known relevance to cancer biology, including CHEK2, RAD54L, NOTCH2, ASXL1, PDGFRA, and KIT." (PMID 40627234, 2025). "Out of 15 known cancer-actionable genes with curated drug resistance data reported in COSMIC database, KIT was the only mutant gene in this cohort with two different missense variants known to be chemoresistant." (PMID 41009531, 2025). "Previous studies have shown that the overexpression of receptor tyrosine kinases such as c-KIT or PDGFR can increase proliferation, migration, and invasion of cancer cells." (PMID 40076604, 2025). "The epidermal growth factor receptor (EGFR) family ErbB1 and ErbB2, stem cell factor (SCF)-KIT, and vascular endothelial growth factor receptor 3 (VEGFR3) pathways, major pathways related to cancer aggressiveness, were downregulated." (PMID 38886756, 2024).
cancer (continued). "Recent studies have reported that RTKs other than KIT, such as FLT3-ITD, PDGFRA, MET, and insulin-like growth factor receptor 1 (IGF-1R), also use the Golgi/TGN as their signaling platform in cancer cells." (PMID 38679330, 2024). "Through this analysis, we identified eight major cell types, namely B cell (CD79A), cancer cell (KRT5), cycling cell (MKI67), endothelial cell (VWF), fibroblast (COL1A1), mast cell (KIT), monocyte/macrophage (CD14) and T cell (CD3D)." (PMID 38279519, 2024). "We observed differential expression of four genes, ALB, KIT, PDGFRB, and TGFBR1, in regular and neighbouring cancer tissues." (PMID 39364054, 2024). "The compounds were further screened for their antiproliferative activity against c-KIT-dependent GIST-T1 and HMC1.2 cancer cell lines." (PMID 37298401, 2023). "Compound 22aa exhibited potent antiproliferative activity against both c-KIT wt-expressing GIST cancer cell line GIST-T1 (GI50 = 0.004 μM) and the c-KIT T670I-expressing GIST cancer cell line GIST-5R (GI50 = 0.026 μM)." (PMID 37298401, 2023). "By the way, an average proportion of GAs for known oncogenes (e.g., KIT, MYC, CTNNB1, MDM2 and APC) in the same pan-cancer cohort ranges from four to 9%." (PMID 37373333, 2023). "CD34+KIT low stem cells for GIST, cancer cell quiescence, and altering the metabolic phenotype of GIST through reactive oxygen species (ROS0 and hypoxia-inducible factor-1α (HIF-1α) can play a role 54–56." (PMID 37545902, 2023). "Compound 35h showed a strong growth inhibition in KIT-dependent GIST cancer cells, such as GIST-T1 and GIST-882 (GI50 = 0.013 and 0.006 μM) and maintained a selectivity window against the GIST-48B cancer cell line (GI50 = 1.37 μM)." (PMID 37298401, 2023). "Cabozantinib is used for cancer treatment and inhibits various receptor tyrosine kinases, including VEGFR, MET, RET, KIT, AXL and FLT332." (PMID 35449173, 2022). "The derivative 6r is capable of strongly inhibiting a c-KIT V560G/D816V double mutant that is resistant to imatinib and remarkably attenuates proliferation of GIST-T1 and HMC1.2 cancer cells." (PMID 36612139, 2022). "Among newly identified genes, eleven other cancer targets were detected: MPL; ERBB4; VHL; FGFR3; KIT; KDR; PTEN; KRAS; PTPN11; ERBB2; and SMARCB1." (PMID 35621644, 2022). "In the present study, we evaluated SCF as an effective vector to target mutant-KIT-driven GIST cancer cells, and the conjugated drug SCF-DM1 was tested for its efficacy in mutant-KIT-driven GIST cells in vitro and in vivo with a xenograft mouse model." (PMID 35999600, 2022). "Most of the pulmonary tuft cell-like cancers of Cohort-J strongly expressed BCL2 and KIT protein, and the percentages of immunoreactive cells were significantly higher in the tuft cell-like than non-tuft cell-like groups (P < 0.05)." (PMID 36402755, 2022). "KIT and PDGFRA play a major role in the oncogenic process in gastrointestinal stroma tumors (GIST) and small molecules have been employed with great success to target the KIT and PDGFRA pathways in this cancer." (PMID 35965531, 2022). "KIT and PDGFR-alpha belong to the type III receptor tyrosine kinase family, members of which can lead to the occurrence of several cancers." (PMID 35999600, 2022). "Of note, KIT+, ALDH1+ and SOX2+ cancer stem cell populations harbor proliferative and epithelial-like characteristics, while CD44+ and SOX9+ cancer stem cell populations demonstrate invasive and mesenchymal-like properties." (PMID 36171192, 2022). "We observed that, among these substances, 6r is capable of inhibiting significantly c-KIT and suppressing substantially proliferation of GIST-T1 cancer cells." (PMID 36612139, 2022). "Frequent copy‐number aberrations were also found for important cancer genes, such as CDKN2A, KIT, MDM2, CCND1, CDK4, and PAK1, among others." (PMID 35229492, 2022). "Mutant KIT retains the ability of binding with SCF, and therefore, SCF can be used as a reasonable vector to deliver cytotoxic drug(s) into GIST cancer cells." (PMID 35999600, 2022).